TLR9 (toll like receptor 9)
Diseases named in the same sentence as TLR9 in open-access papers (continued):
Sharing a sentence is not in itself a finding about the gene and the disease.
gastric cancer (continued). "Association between TLR9 -1486 T/C and gastric carcinoma in relation to H. pylori infection." (PMID 23776537, 2013). "The new strategy can be used for other types of cancer, e.g., oral squamous cell carcinoma expressing TLR9 and gastric cancer expressing TLR4." (PMID 38390872, 2024). "TLR-9, a vital component of our immune system, is found to be significantly involved in the progression of gastric cancer." (PMID 37894471, 2023). "On the contrary, CQ inhibited MGC803 gastric cancer cell migration via the TLR9/NFκB signaling pathway, supporting our results of decreased NFκB in the DRG neurons after intrathecal application of CQ." (PMID 34299065, 2021). "On the other hand, TLR4 rs4986791 as well as TLR9 rs5743844 SNPs though have MAF <0.05, were selected as these polymorphisms have previously been shown to be associated gastric cancer (TLR4) and CpG oligonucleotide hyporesponsiveness (TLR9)." (PMID 31365550, 2019). "In a study among 106 gastric adenocarcinoma patients, TLR3, TLR4, and TLR9 were highly expressed in gastric cancer tissues and survival worsened among patients with a high TLR3 expression." (PMID 31467388, 2019). "The overall survival of gastric cancer patients was analyzed for dependence on TLR9 -1486 genotypes using Kaplan-Meier survival curves." (PMID 23776537, 2013). "In the gastric cancer patients, the TLR9 genotype distribution was 31.33% TT, 51.50% TC, and 17.17% CC in H. pylori-positive patients; and 25.93% TT, 54.32% TC, and 19.75% CC in H. pylori-negative patients." (PMID 23776537, 2013). "Recently, the tissue expressions of TLR1, TLR2, TLR4, TLR5, TLR7 and TLR9 as potential prognostic biomarkers in gastric cancer were reported, showing a positive correlation between each other and a high expression of each studied TLR in tumors with an intestinal-type histology." (PMID 40362298, 2025). "Beyond skin, TLR9 promoter polymorphisms have been associated with risk and prognosis in gastric cancer cohorts, although these findings do not address epithelial protein expression." (PMID 41211638, 2025). "In the case of cancer, particularly gastric cancer, the role that TLR-9 plays in immunosurveillance and shaping the tumor microenvironment suggests that it may be a promising target for therapy and a useful prognostic marker." (PMID 37894471, 2023). "Moreover, overexpression of TLR4, TLR5 and TLR9 not only has been reported in gastric cancer cell lines but also was observed in the metaplastic and dysplastic gastric epithelial cells of patients with Helicobacter pylori gastritis." (PMID 33336901, 2021). "In a word, TLR9 is involved in the occurrence and development of gastric cancer." (PMID 33469538, 2020). "Thus, we aimed to evaluate the tissue expressions of TLR1, TLR2, TLR4, TLR5, TLR7, and TLR9 as potential prognostic biomarkers in gastric cancer." (PMID 31467388, 2019). "To date, there are no functional data available for the TLR9 -1486T/C polymorphism with regard to gastric cancer." (PMID 23776537, 2013). "In this study, we did not detect TLR4+896G, TLR4+1196T, or TLR9 -1237C alleles in gastric cancer patients and healthy controls in the Chinese population." (PMID 23776537, 2013). "TLR expression especially TLR4, and TLR9, may act as a prognostic biomarker in gastric cancer." (PMID 39451226, 2024). "Additionally, the precise mechanisms by which EBV contributes to the development of gastric cancer are still an active area of research, and there may be individual differences in how TLR-9 responds to EBV infection." (PMID 37894471, 2023). "However, the underlying mechanisms that define the role of TLR9 in the onset and progression of H. pylori-triggered gastric cancer are not entirely understood and need to be unraveled in further studies." (PMID 35239059, 2022). "However, TLR9 may also be involved in early promotion of some cancers such as gastric cancer, through enhancement of inflammation and of cell proliferation." (PMID 36714124, 2022).
gastric cancer (continued). "TLR4+896G, TLR4+1196T, and TLR9 -1237C alleles may be very rare, at least in Chinese, Korean, and Japanese populations; thus, this gene may not be a candidate for determining gastric cancer susceptibility in this area." (PMID 23776537, 2013). "By analyzing specific T and B immune cell groups that express TLR-9, along with the levels of soluble TLR-9 in the blood, the study compares these factors between individuals with gastric cancer and healthy volunteers." (PMID 37894471, 2023). "The relationship between Toll-like receptor 9 (TLR-9) signaling and its involvement with Epstein–Barr virus (EBV) in gastric cancer (GC) is complex and currently under study." (PMID 37894471, 2023). "This research sheds light on the interplay between TLR-9, immune cell populations, and EBV in gastric cancer development." (PMID 37894471, 2023). "Increasing expression of TLR2, TLR4, TLR5, and TLR9 in gastric epithelia of children' gastritis; TLR4, TLR5, and TLR9 in adults' gastritis; TLR2, TLR4, and TLR5 in gastric dysplasia; and TLR4, TLR5, and TLR9 in gastric cancer (GC) is found." (PMID 35300405, 2022). "In gastric cancer, TLR2 and TLR9 are thought to account for the invasive abilities of H. pylori-mediated infection, and in papillary thyroid cancer, TLR3 overactivation is linked to cancer progression." (PMID 31314777, 2019). "Invasion and angiogenesis of gastric cancer cells was described to be mediated by cyclooxygenase-2 (COX-2) after TLR2 and TLR9 activation, leading to inflammation and cancer progression." (PMID 26134824, 2015). "Nevertheless, the inflammatory microenvironment that contains cells without polarity can stimulate TLR9 to promote proinflammatory cascades and eventually result in the development of gastric cancer." (PMID 30863783, 2019). "Similar to our findings, that study concluded that TLR4 and TLR9 expression levels did not significantly predict outcome in gastric cancer patients." (PMID 31467388, 2019). "In gastric cancer (GC) patient models, compared to healthy volunteers, the expression of TLR-2, TLR-3, TLR-4, and TLR-9 was significantly elevated in GC patients, with higher TLR expression observed in more advanced GC subtypes." (PMID 41488647, 2025). "Therefore, our study aims to evaluate the expression of Toll-like receptors (TLR-2, TLR-3, TLR-4, and TLR-9) on NK and NKT-like cells in patients with gastric cancer (GC), compare these results with healthy volunteers (HV), and investigate variants depending on the cancer subtype." (PMID 39594809, 2024). "In gastric cancer (GC), TLR2, TLR3, TLR4, and TLR9 are crucial for modulating immune response and tumor progression." (PMID 39451226, 2024). "In addition to TLR5, TLR1, TLR2, TLR4, TLR7, and TLR9 were also expressed in gastric cancer tissues, yet their expression levels did not function as prognostic biomarkers across the entire patient cohort." (PMID 31467388, 2019). "It should be noted that the relationship between TLR-9, EBV, and gastric cancer is complex and not fully understood." (PMID 37894471, 2023).
Obesity (30 papers, 2015 to 2026). Accumulation of substantial excess body fat. "Single nucleotide polymorphisms (SNPs) in TLR9 are associated with susceptibility to obesity and diabetes." (PMID 39158380, 2025). "TLR9 is associated with the development and progression of both obesity and diabetes, which are closely interlinked metabolic disorders." (PMID 39158380, 2025). "Our study also provides insight into the impact of TLR9 in B cells on obesity, associated with immunological, metabolic, and gut microbiological abnormalities." (PMID 38762479, 2024). "Taken together, our data provide important insights into Tlr9 deficiency in B cells in the context of altered gut microbiota in obesity." (PMID 38762479, 2024). "In this study, the authors demonstrate that TLR9 deficiency in B cells is associated with obesity in mice and results in altered frequencies of T and B lymphocyte subsets and gut microbiome dysbiosis." (PMID 38762479, 2024). "Here, we generate B-cell-specific Tlr9-deficient (Tlr9fl/fl/Cd19Cre+/-, KO) B6 mice and model obesity using a high-fat diet." (PMID 38762479, 2024). "Genetic deficiency of Toll like receptor 9 protected mice from insulin resistance in diet-induced obesity." (PMID 35385497, 2022). "Recently, nucleic acid-sensing by various TLRs, in particular by TLR9, has been implicated in obesity and insulin resistance in both murine and human studies." (PMID 35955609, 2022). "An abundance of nucleic acid ligands and a critical role of TLR-9 in obesity-associated inflammation has also been reported previously both in animal models and humans." (PMID 28660492, 2017). "Overall, our study using the mice with Tlr9-deficiency in B cells has delineated cross-talk among TLR9, adaptive immunity and gut microbiota, leading to an enhanced inflammatory milieu and susceptibility to obesity and associated metabolic changes." (PMID 38762479, 2024). "To investigate the role of B cell-TLR9 in obesity, we generated B cell-specific Tlr9-deficient C57BL/6 mice (Tlr9fl/fl/Cd19Cre+/-B6), and studied both Tlr9fl/fl/Cd19Cre+/- B6 mice (designated as KO group) and Tlr9fl/fl/Cd19Cre-/- B6 littermate controls (designated as Ctr group)." (PMID 38762479, 2024). "Understanding the role of the mtDNA/TLR9 axis in lung inflammation induced by saturated fatty acids may provide insights into new mechanisms of various human diseases associated with obesity, which may eventually provide novel therapeutic targets." (PMID 36674451, 2023). "TLR9 deficiency decreases macrophage accumulation into the visceral fat along with the reduction of inflammation in the adipose tissue and the inhibition of the development of obesity-induced insulin resistance." (PMID 36176986, 2022). "In tandem, these results suggest a link between TLR9 and obesity-associated insulin resistance." (PMID 36176986, 2022). "In addition, in the development of obesity-associated metabolic disorders, several reports suggest the role of another endogenous ligand of TLR9 beside self-derived DNA fragments." (PMID 32714475, 2020). "Hence, TLR9-mediated recognition of the circulating self-DNA plays a crucial role in the obesity-associated inflammation and insulin resistance index." (PMID 33643304, 2020). "The identity of such mechanisms are unclear; however, a recent study in mice demonstrated that obesity is associated with the release of cell-free DNA (cfDNA) which could stimulate the resident macrophages via the TLR9 pathway." (PMID 29387386, 2018). "Thus, targeting TLR9 in B cells may have therapeutic potential for prevention and/or treatment of obesity and obesity-associated disorders." (PMID 38762479, 2024). "In a high‐fat diet (HFD)‐induced mice model of obesity, Tlr9−/− mice gain more body weight and exhibit glucose intolerance and insulin resistance compared to wild type (WT) mice, indicating a beneficial role of TLR9 signaling in obesity development." (PMID 39158380, 2025).
Obesity (continued). "Preclinical studies have shown both beneficial and detrimental roles of TLR9 signaling in the development of obesity and diabetes." (PMID 39158380, 2025). "This suggests that TLR9 signaling helps restrain adipose tissue inflammation and mitigate obesity development." (PMID 39158380, 2025). "Recent studies suggest that TLR9 plays an important role in obesity, which is related to tissue inflammation and insulin resistance." (PMID 38762479, 2024). "Taken together, our data indicate that TLR9 in B cells plays an important role in metabolic dysregulation and obesity." (PMID 38762479, 2024). "In this study, we found that gut microbiota link Tlr9 deletion in B cells to obesity and impaired metabolic responses." (PMID 38762479, 2024). "Obesity is a systemic metabolic disorder with diverse etiological factors and our study provides insight in the role of TLR9 in B cells in obesity." (PMID 38762479, 2024). "We identify an important network involving Tlr9, Irf4 and Il-10 interconnecting metabolic homeostasis, with the function of B and T cells, and gut microbiota in obesity." (PMID 38762479, 2024). "Recent studies suggest that TLR9 plays an important role in obesity and related inflammation and insulin resistance in humans and animals." (PMID 38762479, 2024). "To investigate the intrinsic role of TLR9 in B cells in obesity development, we generated a C57BL/6 mouse strain with B lymphocyte specifically deficient in Tlr9 (Tlr9fl/fl/Cd19Cre+/- B6, KO)." (PMID 38762479, 2024). "Activation of TLR9 leads to an increased production of proinflammatory cytokines, and TLR9 signaling in macrophages is involved in obesity-induced insulin resistance." (PMID 37958808, 2023). "Further studies are needed to explore the function of TLR9 in the pathogenesis of obesity-induced insulin resistance." (PMID 36176986, 2022). "Both TLR7 and TLR9 sense nucleic acids and have been postulated to participate in metabolically induced inflammation in the context of obesity and insulin resistance." (PMID 35955609, 2022). "Obesity-induced cell-free DNA fragments released from adipocytes stimulate chronic adipose tissue inflammation and insulin resistance via TLR9 activation." (PMID 35956081, 2022). "In an experimental study Nishimoto and colleagues have proved that ecDNA recognized by the Toll-like receptor 9 is involved in metabolic complications of obesity, at least in mice." (PMID 35385497, 2022). "TLR9 is involved in various inflammatory and metabolic diseases, such as atherosclerosis, obesity, and nonalcoholic steatohepatitis (NASH)." (PMID 35734577, 2022). "Regression analysis stratified by obesity status revealed the independent association of adipose SRA1 expression with MyD88 in NW (N = 12), and with TLR9 in overweight (N = 32) participants." (PMID 36552771, 2022). "In these diseases, TLR9 is activated by various DAMPs, including cell-free DNA in obesity and mtDNA and HMGB1 released from the damaged liver in NASH." (PMID 35734577, 2022). "The literature supports that overactivation of TLR9 under the chronic stress of obesity is a critical driver of the pathogenesis of NASH and NASH-associated fibrosis." (PMID 33584545, 2020). "Obesity induced by high-fat diet (HFD) feeding promoted TLR9 expression in adipose tissue in addition to cfDNA in animal studies." (PMID 32714475, 2020). "The upregulation of TLR9 and its chaperones in concert in obesity suggests an organized effort by the cell for increased TLR9 signaling." (PMID 33584545, 2020). "Of note, TLR9 is reportedly activated by obesity-related DNA-release from adipocytes and is involved in the chronic inflammatory response as well as insulin resistance." (PMID 32437400, 2020). "Genetic deletion of TLR9 decreased the accumulation of macrophages in obese adipose tissue and inhibited the development of obesity-induced adipose tissue inflammation and insulin resistance." (PMID 32714475, 2020).
Obesity (continued). "This aberrant activation of TLR9 during obesity was shown to be mediated by the recognition of self-DNA released by dying adipocytes, MPs loaded with mtDNA as well as ET." (PMID 33574823, 2020). "In a loss-of-function animal study, mitochondrial DNA released by adipocytes under obesity-induced excessive stress stimulates TLR9 in the immune cells and induces inflammation in adipose tissue." (PMID 31582899, 2019). "On the basis of obesity model, we investigated the mRNA expression levels of TLR9/KLF4 and downstream inflammatory-related factors." (PMID 30662369, 2018). "Some studies have reported detrimental effects of TLR9 signaling in obesity." (PMID 39158380, 2025). "However, the role that TLR9 plays in B cells in the context of obesity, and how TLR9 in B cells affects adaptive immunity and gut microbiota in obesity is unclear." (PMID 38762479, 2024). "In obesity, the death of adipocytes leads to an increase of cell-free nucleic acids (cfDNA) in adipose tissue and plasma, and adipose tissue-resident macrophages are involved in the recognition of these elevated cfDNA levels via TLR9." (PMID 37958808, 2023). "The targeted analysis of a subset of jejunum genes in the context of obesity and ME1 expression revealed novel, positive associations of ME1 with two key mediators of intestinal tissue architecture, inflammation, and metabolism, namely TLR9 and FFAR3." (PMID 37047583, 2023). "To explore the role of TLR9 in obese condition, we employed diet-induced obesity mouse model." (PMID 36176986, 2022). "At first, we confirmed that HFD-induced obesity promotes TLR9 expression in the visceral fat." (PMID 36176986, 2022). "Our data further show that TLR3/TLR9 expression was associated independently with the expression of SRA1 in individuals with T2D, while TLR3, TLR7 and IRAK1 were identified as the independent predictors of adipose SRA1 expression in individuals with obesity." (PMID 36552771, 2022). "Furthermore, TLR3/TLR7/IRAK1 and TLR3/TLR9 were identified as independent predictors of AT SRA1 expression in individuals with obesity and T2D, respectively." (PMID 36552771, 2022). "On the one hand it has been suggested that TLR9 may protect against obesity and the metabolic syndrome having an anti-inflammatory effect." (PMID 33519463, 2020). "Blocking TLR9 activity in obese people may reduce obesity-induced adipose inflammation and chances of future development of T2DM." (PMID 33643304, 2020). "TLR9-/- mice with HFD do not show obesity-associated inflammation, macrophage accumulation in the adipose tissue and have better insulin sensitivity than WT mice with HFD." (PMID 33643304, 2020). "In addition, cell-free DNA from obesity-related adipocyte degeneration can activate TLR9." (PMID 31582899, 2019). "And up-regulated genes-NAMPT, TLR9, PTGS2, HBD, and PCSK1N might be associated with obesity risk." (PMID 29132311, 2017). "DEGs of NAMPT, TLR9, PTGS2, HBD, and PCSK1N might be associated with obesity." (PMID 29132311, 2017). "DPR suppressed the expression of TLR4 and TLR9, key receptors that recognize mitochondrial DAMPs, further indicating that DPR limits obesity‐induced inflammaging signaling." (PMID 41549510, 2026). "In this review, we summarize the current knowledge on the roles of TLR9, cGAS‐STING, AIM2, IFI16, DNA‐PK, and DDX41 in obesity, diabetes, fatty liver disease, and cardiovascular disease." (PMID 39158380, 2025). "Thus, we have shown that lack of TLR9 in B cells not only affected systemic B and T cell phenotypes and function but there were also altered gut mucosal antibody profiles and gut microbiota composition, which are closely associated with obesity." (PMID 38762479, 2024). "Although the function of Toll-like receptor 9 (TLR9) in immunity and inflammation is well-established, its role in obesity is less well-studied." (PMID 38762479, 2024).